PLK1 (polo like kinase 1)
Diseases named in the same sentence as PLK1 in open-access papers (continued):
Sharing a sentence is not in itself a finding about the gene and the disease.
tumor (continued). "Promising tumour regression was reported after synergistic effects of a mitotic inhibitor acting on PLK1 (BI2536) to induce mitotic arrest, and a proapoptotic agent (LCL161) to sensitize HCC cells to TNFα-triggered cell death in a murine model of HCC." (PMID 30662724, 2018). "In this study, we found that Plk1 overexpression functions as a tumor suppressor both in vitro and in vivo." (PMID 30069007, 2018). "All together, these data suggest that Plk1 overexpression results in defective mitosis and cytokinesis in mammary gland epithelial cells, thus suppressing tumor development." (PMID 30069007, 2018). "The experimental data revealed the significant accumulation of NPs and resulted in efficient PLK1 silencing that leads to tumor suppression through increased apoptosis." (PMID 29881657, 2018). "In fact, we observe that miR-34a and PLK1 expression is marginally positively correlated (Spearman R = 0.19, P < 0.01), thus our intervention is likely to revert this correlation, lower the tumor's fitness, and lead to improved patient survival." (PMID 29295989, 2018). "In line with the polyploid phenotype observed in cultured MEFs, overexpression of Plk1 resulted in increased nuclear volume in tumor cells." (PMID 30069007, 2018). "Here the authors produce an inducible mouse model to overexpress PLK1 and show that actually this can act as a tumor suppressor by perturbing mitotic progression and cytokinesis." (PMID 30069007, 2018). "Plk1 inhibition with specific small molecule inhibitors is currently considered as an attractive therapeutic strategy against specific tumor types such as leukemia and non-small cell lung cancer." (PMID 30069007, 2018). "Systemic administration of the optimized AsiC in its swap conformation in PSMA-expressing 22Rv1 (1.7) tumor-bearing athymic mice resulted in a significant reduction of tumor growth and Plk1 silencing." (PMID 30340426, 2018). "Similar to the previous model, Plk1 overexpression also prevented tumor development in 45% of the colony and significantly delayed tumor onset in the remaining animals." (PMID 30069007, 2018). "Recently, it was reported to disrupt the interaction of Plk1 with Ras leading to its anti-tumoral effects in tumor cells." (PMID 29541386, 2018). "To analyze if high Plk1 levels influence chromosome instability during tumor growth, we performed time lapse microscopy of tumor cells." (PMID 30069007, 2018). "Each monotherapy of miR-34a/NC-siRNA or PLK1-siRNA/NC-miR inhibited tumor growth to an average of 31% (896.6 ± 91 scaled counts per second) and 44.25% (1278.0 ± 459 scaled counts per second), respectively." (PMID 29295989, 2018). "This siRNA is targeted against polo-like kinase 1 (PLK1), a protein that plays a key role in tumour cell proliferation." (PMID 28346375, 2017). "To this end, we chose Polo-like kinase 1 (PLK1) as a model target, which is involved in cell division and overexpressed in multiple tumor types." (PMID 28641400, 2017). "Among these GC samples, the immunoreactivity score (IRS) indicated that PLK1 protein expression was significantly higher in the 43 GC samples (9.42±3.06) than in adjacent non-tumor tissues (7.02±3.17, P=0.001)." (PMID 29190933, 2017). "Cationic liposomes were linked to aptamers by the post-insertion method and were used to deliver therapeutic CRISPR/Cas9 that target the survival gene, polo-like kinase 1, in tumor cells." (PMID 28030843, 2017). "Recent studies suggest that targeting PLK1 by small molecule inhibitors is a promising approach to tumor therapy." (PMID 29228610, 2017). "Inhibition of PLK1 expression prevents tumour cell growth and thereby inhibits cancer cell proliferation." (PMID 28346375, 2017). "As previously reported, stable overexpression of Plk1 increased tumor size and tumor mass in Hep3B cells compared with control empty vector group." (PMID 29138396, 2017).
tumor (continued). "The protein entered the spotlight as target molecule for several tumor types, and our data support the important role of PLK1 in HNSCC cells as well." (PMID 29228663, 2017). "In this review, we will summarize the recent advancements in our understanding of the oncogenic functions of PLK1, with a focus on its role in epithelial-mesenchymal transition and tumor invasion." (PMID 28953239, 2017). "Several small molecule inhibitors of PLK1 are being evaluated in clinical trials and we selected four of these compounds to test on tumor (VU-SCC-120 and UM-SCC-22A) and preneoplastic (VU-preSCC-M3) cell lines, as well as on primary keratinocytes." (PMID 29228663, 2017). "When we applied siRNA-mediated PLK1 knockdown, differences in response were observed between tumor and premalignant cells versus primary cells." (PMID 29228663, 2017). "It has been reported that PLK1 also interacts with other tumor suppressors such as CHK2, BRCA1/2, ATM and ATR, BUB1B or BUBR1, CYLD, REST, and TSC1/2." (PMID 28953239, 2017). "Array-based screening with a panel of tumor-lethal small interfering RNAs (siRNAs) identified Polo-like kinase 1 (PLK1) as essential for survival of preneoplastic cells." (PMID 29228663, 2017). "PLK1 is overexpressed in a variety of tumor types and a number of studies indicate a correlation between the level of PLK1 expression in tumors and prognosis." (PMID 29228663, 2017). "Plk1 inhibitors reduce tumor proliferation, but have little effect on normal cells based on the results from mouse xenograft models." (PMID 27902479, 2017). "Taken together, these results demonstrate that G6PD and its phosphorylation-related activation are critical for Plk1-mediated tumor growth in vitro and in vivo." (PMID 29138396, 2017). "They found that siPLK1 with MWCNTs facilitated its internalization by tumor cells in solid tumor mass in vivo, resulting in significant PLK1 knockdown compared to cationic liposome complexes, even though the latter complexes are usually injected systemically." (PMID 28212271, 2017). "These modifications significantly improved the ability of the chimera to reduce tumor size and/or to decrease PLK1 expression." (PMID 29218233, 2017). "In this study, PLK1 was selected as promising target gene, since its suppression resulted in profound growth inhibiting effects in both tumor and preneoplastic cells but much less in primary cells." (PMID 29228663, 2017). "Western blotting using the tumor tissue lysates confirmed the knockdown of Plk1 and the overexpression of G6PD WT and mutants in HeLa xenografts." (PMID 29138396, 2017). "PLK1, a key regulator of mitotic entry, is considered to be an oncology target in several tumor types, including BC." (PMID 28915707, 2017). "Silencing of the targeted PLK1 mRNA and protein in human tumor xenografts with the C15-PEG-CS NPs was approximately 50% of that in the control siRNA group." (PMID 29218233, 2017). "The targeted NP augmented uptake significantly in Her2+ xenografts, had greater silencing of PLK1, and reduced tumor size to a greater extent than did untargeted NPs." (PMID 29218233, 2017). "Our recent study has provided direct evidence of the pro-invasive activity of PLK1 in tumor progression." (PMID 28953239, 2017). "PLK1 has been found to be overexpressed in many types of malignant human tumors and facilitate tumor cell proliferation." (PMID 28724602, 2017). "On the other hand, miR-296-5p has been reported to function as both tumour suppressive and oncogenic miRNA through controlling the expression of p21 and PLK1 respectively." (PMID 28076852, 2017). "While negatively regulating tumor suppressors, PLK1 also intensively interplays with numerous oncogenes." (PMID 28953239, 2017).
tumor (continued). "First, by mining online databases (TCGA, GEO, and Oncomine databases), 19 datasets were obtained, which provided PLK1 mRNA expression values in GC tissues and adjacent non-tumor tissues." (PMID 29190933, 2017). "Further studies are required to evaluate the anti-tumor effects of Aurora A and Plk1 inhibitors after Bora blockade." (PMID 28402276, 2017). "Fast intracellular trafficking of HA-PSR nanoparticles maximized the synergistic cytotoxicity of PTX and PLK1-siRNA for remarkable tumor suppression." (PMID 34322587, 2017). "Western blotting using the tumor tissue lysates confirmed the overexpression of Plk1 and the knockdown of G6PD by shRNAs in Hep3B xenografts." (PMID 29138396, 2017). "Inhibiting PLK1 in xenografts or cell lines deriving from osteosarcoma and medulloblastoma, another embryonal tumor of childhood, suppressed proliferation and induced apoptosis." (PMID 28036269, 2017). "In summary, this meta-analysis supported the conclusion that PLK1 expression confers a useful predictive factor for larger tumor size and positive lymph node status, in addition to higher tumor grading." (PMID 28915707, 2017). "We found higher expression of PLK1 in all tumor samples, with on average a 2.26-fold increase compared to normal mucosa (P<0.0001 Student t test)." (PMID 29228663, 2017). "Significant heterogeneity existed in the correlations between high PLK1 expression and tumor grading (I2 = 78.90%, P < 0.0001)." (PMID 28915707, 2017). "For example, Liu and colleagues found miR-100 functions as a tumor suppressor by post-transcriptionally regulating PLK1." (PMID 27893417, 2017). "Using the DIPG tumor cells, we inhibited PLK1 using a clinically relevant specific inhibitor BI 6727 and evaluated the effects on, proliferation, apoptosis, induction of DNA damage and radio sensitization of the DIPG tumor cells." (PMID 27538997, 2016). "We observed decreased expression levels of genes associated with DNA repair (MRE11, RAD51) and genes involved in cell cycle and chromosomal segregation (PLK1) after FOXM1 inhibition in both GBM tumor cells and stem cells." (PMID 27764801, 2016). "In conclusion, the results presented here suggest that the tumor suppressor potential of SLAMF3 occurs through activation of RB that represses PLK1." (PMID 26799423, 2016). "IHC analysis of ER maleate treated tumor tissues showed a decrease in PLK1, Syk and Cyclin D1 expression, demonstrating that our in vitro findings were reproduced in vivo as well." (PMID 26934445, 2016). "BI-2536, a selective inhibitor of PLK1, effectively inhibits different types of tumour in phase II clinical trials." (PMID 27193833, 2016). "The effect of Plk1 inhibition in tumor cells is well characterized: it induces monopolar spindles, mitotic arrest and apoptosis, leading further to reduced proliferation in vitro and inhibited tumor growth in vivo." (PMID 27713178, 2016). "Our xenograft studies showed that PLK1 overexpression in human prostate epithelial cells leads to cellular transformation in vitro and promotes tumor formation in NSG mice, which suggests that PLK1 has a tumor-promoting role in the prostate." (PMID 27003818, 2016). "While the genomic analysis revealed two classes of PP2A subunits, to selectively target tumor cells that overexpress mitotic genes like PLK1, we decided to take a systematic approach to identify SDL interactions." (PMID 27557495, 2016). "Polo-Like Kinase 1 (PLK1), a serine-threonine kinase that is often overexpressed across multiple tumor types, is one of the key regulators of CIN and is considered as a potential therapeutic target." (PMID 27557495, 2016). "We examined the expression of PLK1 mRNA in DIPG tumor samples through microarray analysis and found it to be up regulated versus normal pons." (PMID 27538997, 2016). "The in vitro introduction of siRNA against PLK1 in Huh-7 cells increased apoptosis in caspase-independent pathway and induced tumor regression in siPLK1-treated mice." (PMID 26799423, 2016).
tumor (continued). "Based on the results of our tumor xenograft experiments implicating PLK1 in PCa metastasis, we next investigated the role of PLK1 in regulating prostate epithelial cell motility in vitro." (PMID 27003818, 2016). "These include a number of genome maintenance genes such as MCM subunits, Plk1, Wee1, Bub1 or cyclins that are also downregulated by the vGPCR and miR-34a in our tumor model." (PMID 26871287, 2016). "The Cox proportional HR for PLK1 expression taking into account the residual tumor status was 1.626 (95 % confidence interval 1.124–2.351, p = 0.00979)." (PMID 26754547, 2016). "Cox regression univariate analyses showed higher TP PLK1 score, higher age, higher tumour T stage, metastatic status, presence of vascular and perineural invasion and absence of adjuvant chemotherapy to be significant predictors of worse OS." (PMID 26047016, 2015). "Immunohistochemical staining for PLK1 expression in tumor tissue indicated there was a decrease in PLK1 levels in areas of lung tumors collected from mice treated with iNOP-7-PLK1 siRNA when compared to controls." (PMID 25557168, 2015). "Given the perspective of fostering the susceptibility to undergo apoptosis of either CPT-sensitive or –resistant tumor cells, we explored the therapeutic potential of a combination treatment with CPTs and PLK1 kinase inhibitors." (PMID 25826089, 2015). "In summary, p21 is crucial to determine the fate of tumor cells treated with Plk1 inhibitors, in particular Poloxin." (PMID 25483104, 2015). "Here, we explored the role of PLK1 in the sensitivity of cell lines of different tumor types to SN38 and evaluated pharmacological inhibition of PLK1 in preclinical models as an approach to enhance CPT11 antitumor activity and overcome drug resistance." (PMID 25826089, 2015). "Our data suggest that the Cdk-interacting protein p21 is a useful biomarker for predicting the efficacy of Plk1 inhibition in tumor cells." (PMID 25483104, 2015). "Plk1 inhibitors are currently undergoing various clinical trials, it is thus important to study its response in tumor cells after a long-term treatment." (PMID 25483104, 2015). "In line with these notions, our data indicate that the presence of functional p21 facilitates the survival of tumor cells upon Plk1 inhibitor treatment by conferring resistance to mitotic arrest and protection against apoptosis." (PMID 25483104, 2015). "Small molecule inhibitors for PLK-1 showed substantial inhibitory potential against tumor and induced the apoptosis." (PMID 26557691, 2015). "Kaplan-Meier survival analysis revealed that shorter survival time correlated with high tumor PLK1 expression (p = 0.002)." (PMID 25574601, 2015). "The effect of Plk1 inhibition is well characterized, it induces mitotic arrest and apoptosis, leading further to a reduced proliferation in vitro and inhibited tumor growth in vivo." (PMID 25483104, 2015). "These insights have initiated the design of various types of small molecules to downregulate and/or inhibit the overexpression of PLK-1 and regress tumor growth." (PMID 26557691, 2015). "Univariate analyses and multivariate model of tumour periphery (TP) polo-like kinase 1 (PLK1) scores with clinicopathological variables for survival outcomes." (PMID 26047016, 2015). "Plk1 is upregulated in a range of human tumours; thus targeting Plk1 is an attractive therapeutic strategy and a number of inhibitors are under clinical evaluation including BI2536." (PMID 26491220, 2015). "Human polo-like kinase 1 (Plk-1) plays a pivotal role in mitosis in normal and malignant cells and preclinical studies have highlighted the importance of Plk-1 in tumor development." (PMID 25784931, 2015).
tumor (continued). "Paclitaxel combined with siRNA complexes against VEGF and PlK-1 was used in studies using multifunctional cationic micelles, resulting in increased endocytosis in tumor cells and higher tumor suppression." (PMID 28347089, 2015). "A number of PLK1 inhibitors are in clinical trial; however, poor tumor bioavailability and off-target effects limit their efficacy." (PMID 25557168, 2015). "Survival analysis revealed that low PLK1 score in the tumour periphery had a hazard ratio of death of 0.59 in multivariate analysis." (PMID 26047016, 2015). "For an effective anticancer therapy, it is desirable to ensure that the damage induced by small molecule compounds like Plk1 inhibitors is strong enough to drive tumor cells undergoing apoptosis otherwise a drug resistance phenotype will be provoked." (PMID 25483104, 2015). "In the same fashion, the FOXM1 target gene PLK1 has also been shown to be overexpressed in a wide range of tumours, including oesophageal adeno- and squamous carcinomas." (PMID 26576650, 2015). "We found variable expression of PLK1 in the centre and periphery of the primary tumour, and in nodal deposits." (PMID 26047016, 2015). "TAK-960 is another novel PLK1 inhibitor that has shown activity in several tumor cell lines, including those cells highly expressed multidrug-resistant protein 1 (MDR1)." (PMID 25574601, 2015). "Meanwhile, we found that, even in the same HCC sample, different levels of PLK1 distributions in different subgroup of tumor cells were detected." (PMID 25019081, 2014). "Strong anti-tumor activity was observed using both small molecule Plk1 inhibitors characterized by tumor stasis over the 21 day study." (PMID 25365521, 2014). "As a further biological readout of senescence, we examined the effect of prolonged treatment with Plk1 inhibitors on tumor morphology in vivo." (PMID 25365521, 2014). "PLK1 is up-regulated in many different tumour tissues like head and neck squamous cell carcinoma, oesophagus and stomach cancer, ovarian cancer, non-small cell lung cancer, liver cancer, cervical cancer and breast cancer." (PMID 24767679, 2014). "Overexpression of PLK1 has been found in a number of human tumours and PLK1 miRNA is proposed to be the target of miR-100." (PMID 24106980, 2013). "As reported for other solid cancers, Plk1 protein levels in GBM are higher compared to lower-grade tumours or normal tissues." (PMID 24204733, 2013). "In support of these interesting data, Plk1 is highly expressed in a broad spectrum of human tumors and its expression often correlates with poor prognosis of tumor patients, suggesting its involvement in oncogenesis and its potential as a therapeutic target." (PMID 23948487, 2013). "This is due either to higher proportions of cycling cells in the tumour population or higher Plk1 levels within individual cells." (PMID 24204733, 2013). "This new in vivo model of CD56+ AML that recapitulates the human tumour lends support for the therapeutic use of PLK1 inhibitors in AML." (PMID 23520509, 2013). "In accordance with this idea, mice heterozygous for plk1 developed tumors at threefold greater frequency than their wild-type counterparts, suggesting that plk1 functions as a haploinsufficient tumor suppressor." (PMID 24349352, 2013). "Core promoters with adjacent regions of the human genes CDC6, POLD1, CKS1B,MCM2, and PLK1 were cloned into a pGL3 vector in front of the Photinus pyrailsgene Luc in order to study the tumor specificity of the promoters." (PMID 24303203, 2013).